RENBP (renin binding protein)
Description:
Catalyzes the interconversion of N-acetylglucosamine to N-acetylmannosamine. Involved in the N-glycolylneuraminic acid (Neu5Gc) degradation pathway: although human is not able to catalyze formation of Neu5Gc due to the inactive CMAHP enzyme, Neu5Gc is present in food and must be degraded.
Synonyms: RnBP; RBP
Tractability: PROTAC: ubiquitination databases record sites on it; its protein half-life has been measured.
Gene: Protein-coding gene on chromosome X (153,935,269 to 153,944,687, reverse strand). Ensembl gene ENSG00000102032.
Pathways (Reactome):
Metabolism of proteins: Synthesis of UDP-N-acetyl-glucosamine
Gene Ontology:
Molecular function: identical protein binding; N-acylglucosamine 2-epimerase activity; peptidase inhibitor activity; protein binding; endopeptidase inhibitor activity; isomerase activity
Biological process: N-acetylneuraminate catabolic process; regulation of blood pressure; amino sugar metabolic process; carbohydrate metabolic process
Cellular component: extracellular exosome; cytosol
Homologues: Orthologues: chimpanzee RENBP (99% identical), macaque RENBP (95% identical), rabbit RENBP (88% identical), mouse Renbp (83% identical), pig RENBP (82% identical), rat Renbp (78% identical), tropical clawed frog renbp (60% identical), zebrafish renbp (58% identical).
Diseases named in the same sentence as RENBP in open-access papers:
RENBP is named in the same sentence as 6 diseases in open-access papers, as found by Europe PMC text mining. Sharing a sentence is not in itself a finding about the gene and the disease. The quoted sentences say what the papers report.
colon cancer (1 paper, 2017). "TYMS, SHMT2, GALT, RENBP, and AMDHD2 were among the metabolic genes that had an unfavorable expression in colon cancer, meaning that their high expression in patients treated with 5-FU was associated with poorer prognosis." (PMID 29026541, 2017).
schizophrenia (1 paper, 2018). A major psychotic disorder characterized by abnormalities in the perception or expression of reality. "Nonetheless, a subset of PD (e.g., SLC50A1), ALS (ITPR2), and schizophrenia (RENBP) susceptibility genes were part of the microglia signature in the aged human brain." (PMID 29416036, 2018).
RENBP also shares sentences with these, for which no sentence is quoted: atherosclerosis (1 paper); autoimmune disease (1); Glucose intolerance (1); Insulin resistance (1).